CYP2A7 (cytochrome P450 family 2 subfamily A member 7)
Description:
Cytochromes P450 are a group of heme-thiolate monooxygenases. In liver microsomes, this enzyme is involved in an NADPH-dependent electron transport pathway. It oxidizes a variety of structurally unrelated compounds, including steroids, fatty acids, and xenobiotics.
Synonyms: CYP2A; CPA7; CPAD; CYPIIA7; P450-IIA4
Tractability: Small molecule: it belongs to a druggable protein family. Antibody: UniProt places it where antibodies can reach, with medium confidence. PROTAC: its protein half-life has been measured; a small molecule that binds it is known.
Gene: Protein-coding gene on chromosome 19 (40,875,432 to 40,882,752, reverse strand). Ensembl gene ENSG00000198077.
Subcellular location: Endoplasmic reticulum membrane; Microsome membrane
Pathways (Reactome):
Metabolism: CYP2E1 reactions; Fatty acids; Xenobiotics
Gene Ontology:
Molecular function: arachidonate epoxygenase activity; heme binding; oxidoreductase activity, acting on paired donors, with incorporation or reduction of molecular oxygen, reduced flavin or flavoprotein as one donor, and incorporation of one atom of oxygen; oxygen binding; iron ion binding; monooxygenase activity; oxidoreductase activity, acting on paired donors, with incorporation or reduction of molecular oxygen
Biological process: coumarin metabolic process; epoxygenase P450 pathway; xenobiotic metabolic process
Cellular component: cytoplasm; endoplasmic reticulum membrane
Genetic constraint (gnomAD): Loss-of-function variants: 36 observed, 41.06 expected, observed/expected ratio (o/e) 0.88, 90% interval 0.67 to 1.16. The upper end of that interval is the gene's LOEUF score, 1.16, which puts it in group 5 of 6, group 1 being the genes least tolerant of losing a copy. Missense variants: 661 observed, 615.43 expected, observed/expected ratio (o/e) 1.07, 90% interval 1.01 to 1.14. Synonymous variants: 260 observed, 239.15 expected, observed/expected ratio (o/e) 1.09, 90% interval 0.98 to 1.21.
Homologues: Orthologues: chimpanzee CYP2A7 (98% identical), macaque CYP2A24 (91% identical), macaque CYP2A29 (90% identical), macaque CYP2A23 (87% identical), dog CYP2A13 (87% identical), pig CYP2A19 (85% identical), rat Cyp2a3 (84% identical), dog CYP2A7 (84% identical), mouse Cyp2a5 (84% identical), rabbit CYP2A10 (83% identical), mouse Cyp2a4 (82% identical), mouse Cyp2a12 (71% identical), and 3 more. Paralogues in human: CYP2A6 (94% identical), CYP2A13 (91% identical), CYP2B6 (51% identical), CYP2F1 (50% identical), CYP2C19 (49% identical), CYP2C8 (48% identical), CYP2C18 (48% identical), CYP2C9 (48% identical), CYP2S1 (47% identical), CYP2E1 (45% identical), CYP2J2 (39% identical), CYP2U1 (38% identical), and 3 more.
Diseases named in the same sentence as CYP2A7 in open-access papers:
CYP2A7 is named in the same sentence as 15 diseases in open-access papers, as found by Europe PMC text mining. Sharing a sentence is not in itself a finding about the gene and the disease. The quoted sentences say what the papers report.
breast carcinoma (3 papers, 2017 to 2025). "For instance, CYP4Z2P maintains the stemness of breast cancer cells, and pseudogene CYP2A7 affects CYP2A6 expression in human liver." (PMID 33931030, 2021). "Eight of these 29 (28%) CNV loci were confirmed by qPCR and/or Nanostring analysis, including four loci that were associated with breast cancer (GTF2H2, ZNF385B, NAALADL2 and PSG5) and two loci that were associated with ovarian cancer (CYP2A7 and OR2A1)." (PMID 28145423, 2017). "These include four loci that were associated (unadjusted P<0.05) with breast cancer (GTF2H2, ZNF385B, NAALADL2 and PSG5), and two loci associated with ovarian cancer (CYP2A7 and OR2A1)." (PMID 28145423, 2017). "With the exception of the CYP2A7 locus (P=0.007), all validated CNV regions returned a modest association (P-values ranged from 0.01 to 0.049) for ovarian or breast cancer risk." (PMID 28145423, 2017). "However, more research is needed to better understand the molecular roles of CYP2A6 and CYP2A7 in breast cancer." (PMID 40860340, 2025).
lung carcinoma (3 papers, 2015 to 2025). "SNPs near CYP2A7 and CYP2A6 on chromosome 19 have been associated with lung cancer, cigarette smoking, and COPD." (PMID 26634245, 2015).
bladder cancer (2 papers, 2016 to 2019). "The amplification of CYP2A6 and CYP2A7 (copy number 3 or more) could be merely detected in one bladder cancer cell line." (PMID 27902773, 2016). "Cytochrome P450 enzymes such as CYP2A7 and CYP2A13 score highly as well, and these genes are implicated in bladder cancer but not normally expressed in breast tissue." (PMID 31014259, 2019).
leukopenia (2 papers, 2020). "Recently, a novel association between CYP2A7 rs73032311 variant and 6-MP-induced leukopenia was reported in subjects with both WT NUDT15 and TPMT." (PMID 32611418, 2020). "Finally, the combination of NUDT15, TPMT, and CYP2A7 variants improves predictive sensitivity of 6MP-induced leukopenia from 70.7% to 85.4%, but decreases the specificity (91.7% vs. 70.7%)." (PMID 32265697, 2020). "Considering CYP2A7 is highly expressed in the liver, which is the main organ in which thiopurine is metabolized, the details on the mechanism of how the variant in CYP2A7 impacts on 6MP-induced leukopenia are needed to be further elucidated." (PMID 32265697, 2020).
hepatocellular carcinoma (1 paper, 2023). A malignant tumor that arises from hepatocytes. "In hepatocellular carcinoma (HCC), a gene conversion event between CYP2A6 and its pseudogene (CYP2A7) results in the CYP2A61B polymorphism, which carries a fragment from CYP2A7 in the 3′ UTR region." (PMID 37627052, 2023).
ovarian carcinoma (1 paper, 2017). A malignant neoplasm originating from the surface ovarian epithelium. "The strongest association with a validated deletion was observed for ovarian cancer, detected in 75/1962 (3.8%) unaffected carriers and 4/357 (1.1%) affected carriers (RR=0.50, P=7 × 10−3) overlapping the CYP2A7 locus (19q13.2)." (PMID 28145423, 2017). "A notable finding was an association of a CNV deletion at the CYP2A7 locus (19q13.2) with decreased ovarian cancer risk (RR=0.50, P=0.007)." (PMID 28145423, 2017). "An interesting finding from this study was an association of a validated CNV deletion at the CYP2A7 locus (19q13.2) with decreased ovarian cancer risk (relative risk=0.50, P=0.007)." (PMID 28145423, 2017).
thymoma (1 paper, 2017). A neoplasm arising from the epithelial cells of the thymus. "The characteristic members of this group are GIF, CYP2A7, LCN1, as well as GAD2, the expression of which followed AIRE’s expression pattern in thymomas, and conceivably CT-As, for which AIRE-dependency in human thymus remains unknown." (PMID 28861084, 2017).
triple-negative breast carcinoma (1 paper, 2025). An invasive breast carcinoma which is negative for expression of estrogen receptor (ER), progesterone receptor (PR), and human epidermal growth factor receptor 2 (HER2). "In addition, CYP2A7 is involved in hormone-related metabolic pathways and is closely related to the prognosis of patients with triple-negative breast cancer." (PMID 40860340, 2025).
tumor (7 papers, 2017 to 2025). "The direct interaction between Cyt c and CETP, CLEC11A, CYP2A6 and CYP2A7 has not been clearly revealed, but they have potential indirect associations in cholesterol metabolism, mitochondrial function, oxidative stress regulation and tumor microenvironment regulation." (PMID 40860340, 2025). "We report that the CYP genes with highest expression, ranked by the mean expression in tumor tissues for all patients, are: CYP1B1 (mean normalized expression 112.8), CYP4Z1 (92.2), CYP2A6 (75.7), CYP4X1 (65.1), CYP4B1 (31.5), CYP2A7 (30.8), and CYP4F8 (11.6)." (PMID 28684774, 2017). "It is interesting to note that the only gene within the genomic deletion at 19q13 is CYP2A7, a member of a nicotine-metabolizing family of enzymes that was not previously considered as a typical tumour suppressor." (PMID 28306719, 2017). "Conversely, hepatic periportal markers (e.g., ALDOB, HAL, ASS1) and a subset of CYP-related proteins (e.g., CYP2A6, CYP2A7, CYP2B6) were either absent or downregulated in the tumor region." (PMID 39567475, 2024).
cancer (2 papers, 2022 to 2025). A tumor composed of atypical neoplastic, often pleomorphic cells that invade other tissues. "In this study, we identified three novel CYP2A7/CYP2A6 hybrids in Japanese patients with cancer." (PMID 41272073, 2025).
CYP2A7 also shares sentences with these, for which no sentence is quoted: familial colorectal cancer (1 paper); osteosarcoma (1); prostate carcinoma (1); serous ovarian tumors (1); skin cancer (1).